CORO7 (coronin 7)
Description:
F-actin regulator involved in anterograde Golgi to endosome transport: upon ubiquitination via 'Lys-33'-linked ubiquitin chains by the BCR(KLHL20) E3 ubiquitin ligase complex, interacts with EPS15 and localizes to the trans-Golgi network, where it promotes actin polymerization, thereby facilitating post-Golgi trafficking. May play a role in the maintenance of the Golgi apparatus morphology.
Synonyms: Crn7; FLJ22021; POD1; 0610011B16Rik
Tractability: PROTAC: UniProt records ubiquitination sites on it; ubiquitination databases record sites on it; its protein half-life has been measured.
Gene: Protein-coding gene on chromosome 16 (4,354,542 to 4,425,705, reverse strand). Ensembl gene ENSG00000262246.
Subcellular location: Golgi apparatus membrane; Golgi apparatus, trans- Golgi network; Cytoplasmic vesicle; Cytoplasm, cytosol
Gene Ontology:
Molecular function: actin binding; protein binding; actin filament binding
Biological process: actin filament polymerization; Golgi to endosome transport; positive regulation of hippo signaling; actin filament organization; cell migration
Cellular component: membrane; trans-Golgi network; actin filament; Golgi apparatus; plasma membrane; cytoplasmic vesicle; cytosol; Golgi membrane
Genetic constraint (gnomAD): Loss-of-function variants: 107 observed, 115.37 expected, observed/expected ratio (o/e) 0.93, 90% interval 0.79 to 1.09. The upper end of that interval is the gene's LOEUF score, 1.09, which puts it in group 4 of 6, group 1 being the genes least tolerant of losing a copy. Missense variants: 1,314 observed, 1,188.5 expected, observed/expected ratio (o/e) 1.11, 90% interval 1.06 to 1.16. Synonymous variants: 603 observed, 515.4 expected, observed/expected ratio (o/e) 1.17, 90% interval 1.09 to 1.25.
Homologues: Orthologues: chimpanzee CORO7 (98% identical), macaque CORO7 (97% identical), rabbit CORO7 (87% identical), guinea pig CORO7 (86% identical), mouse Coro7 (86% identical), dog CORO7 (85% identical), rat Coro7 (84% identical), pig CORO7 (83% identical), tropical clawed frog coro7 (56% identical), zebrafish coro7 (42% identical), Drosophila melanogaster pod1 (38% identical), Caenorhabditis elegans pod-1 (31% identical), and 1 more. Paralogues in human: CORO1A (17% identical), CORO1B (17% identical), CORO1C (17% identical), CORO6 (17% identical), CORO2A (17% identical), CORO2B (16% identical).
Diseases named in the same sentence as CORO7 in open-access papers:
CORO7 is named in the same sentence as 17 diseases in open-access papers, as found by Europe PMC text mining. Sharing a sentence is not in itself a finding about the gene and the disease. The quoted sentences say what the papers report.
Obesity (3 papers, 2015 to 2022). Accumulation of substantial excess body fat. "The hypothalamus is a major part of the energy homeostasis network, considering that CORO7 was presented as a gene that is associated with obesity, it is very interesting that we find Coro7 positive neurons to such a high degree within the hypothalamus." (PMID 25887538, 2015). "Additionally, lower DNAm at a CpG site near CORO7 has been associated with obesity in youths." (PMID 35395780, 2022).
schizophrenia (2 papers, 2023 to 2024). A major psychotic disorder characterized by abnormalities in the perception or expression of reality. "Many of these genes have been previously linked to brain-related disorders, including Alzheimer’s disease (WDR12, AGFG2, and CDK5RAP3), schizophrenia (SRA1, WDR55, CORO7, DDAH2, PCDHA8), autism spectrum disorder (MAPK3, PCDHA13), and major depressive disorder (ZMAT2 and ITIH4)." (PMID 39269986, 2024).
bipolar disorder (1 paper, 2015). A disorder of the brain that causes unusual shifts in mood, energy, activity levels and the ability to carry out day-to-day tasks. "We identified three rare deletions in KCNJ6, UNC13C, OTOL1 and 7 rare duplications in CNTNAP2/MIR548F3, CORO7/VASN, DTNB, EMID2, KCNF1, PDPR and SGTA/THOP1 that are present in children with bipolar disorder (and their parents)." (PMID 25887117, 2015).
oral squamous cell carcinoma (1 paper, 2021). "The Cancer Genome Atlas (TCGA) analysis revealed that CORO1C, CORO2A, and CORO7 were significantly upregulated in oral squamous cell carcinoma (OSCC) tissues (p < 0.05)." (PMID 34884487, 2021).
pancreatic ductal adenocarcinoma (1 paper, 2023). An infiltrating adenocarcinoma that arises from the epithelial cells of the pancreas. "Analysis of large cohort data from The Cancer Genome Atlas revealed that expression of CORO1A, CORO1B, CORO1C, CORO2A, and CORO7 was significantly upregulated in pancreatic ductal adenocarcinoma (PDAC) tissues (p < 0.05)." (PMID 37239355, 2023).
thyroid disease (1 paper, 2022). "No previous association with thyroid disease has been reported for the remaining five proteins: sialic acid acetylesterase (SIAE), hepatocyte growth factor-regulated tyrosine kinase substrate (HGS), Myotrophin (MTPN), 60S ribosomal protein L24 (RPL24), and Coronin-7 (CORO7)." (PMID 36068205, 2022).
cancer (1 paper, 2021). A tumor composed of atypical neoplastic, often pleomorphic cells that invade other tissues. "For other coronin families that have not been analyzed in this study (especially, CORO1C, CORO2B, and CORO7 whose expressions are dysregulated in cancer tissues), it is essential to elucidate the molecular pathogenesis of OSCC." (PMID 34884487, 2021).
skeletal dysplasia (1 paper, 2014). Any Mendelian diseases that affects growth and development of the skeleton. "On the other hand, the implication of the fusion protein CORO7-MAGMAS in the pathogenesis of the skeletal dysplasia has been ruled out, as the related transcript was not well expressed in human fetal chondrocytes and human osteoblasts." (PMID 24786642, 2014).
tumour (1 paper, 2022). "The qPCR results confirmed the upregulation of Coro7 (p = 0.04), Ccl4 (non-significant) and Gcnt2 (p = 0.011) in the caerin treated tumour bearing mice when compared to untreated mice." (PMID 36497272, 2022).
CORO7 also shares sentences with these, for which no sentence is quoted: Alzheimer disease (1 paper); Anxiety (1); autism spectrum disorder (1); Borderline personality disorder (1); cerebellar ataxia (1); major depressive disorder (1); thyroid cancer (1); thyroid nodule (1).